OR4F5 (olfactory receptor family 4 subfamily F member 5)
Description:
Odorant receptor.
Gene: Protein-coding gene on chromosome 1 (65,419 to 71,585, forward strand). Ensembl gene ENSG00000186092.
Subcellular location: Cell membrane
Pathways (Reactome):
Sensory Perception: Expression and translocation of olfactory receptors
Genetic constraint (gnomAD): Loss-of-function variants: 0 observed, 0.54 expected, observed/expected ratio (o/e) 0, 90% interval 0 to 1.83. That is too few expected variants to judge how well the gene tolerates losing a copy. Missense variants: 15 observed, 17.36 expected, observed/expected ratio (o/e) 0.86, 90% interval 0.58 to 1.33. Synonymous variants: 7 observed, 7.39 expected, observed/expected ratio (o/e) 0.95, 90% interval 0.54 to 1.69.
Homologues: Orthologues: rat Or4f4b (80% identical), mouse Or4f4-ps1 (79% identical), mouse Or4f4b (79% identical), mouse Or4f17 (78% identical). Paralogues in human: OR4F4 (98% identical), OR4F17 (93% identical), OR4K1 (57% identical), OR4F6 (56% identical), OR4K15 (55% identical), OR4F15 (55% identical), OR4F16 (54% identical), OR4F21 (54% identical), OR4F29 (54% identical), OR4F3 (54% identical), OR4K17 (54% identical), OR4K13 (54% identical), and 116 more.
Diseases named in the same sentence as OR4F5 in open-access papers:
OR4F5 is named in the same sentence as 1 disease in open-access papers, as found by Europe PMC text mining. Sharing a sentence is not in itself a finding about the gene and the disease. The quoted sentences say what the papers report.
melanoma (1 paper, 2021). A malignant, usually aggressive tumor composed of atypical, neoplastic melanocytes. "Apart from that, such mutation patterns have been identified in melanoma associated genes, like OR4F5 and SAMD11, validating the specific role of such mutational patterns in melanoma." (PMID 34513841, 2021).